EGFR (epidermal growth factor receptor)
Diseases named in the same sentence as EGFR in open-access papers (continued):
Sharing a sentence is not in itself a finding about the gene and the disease.
tumor (continued). "PHD3 knockdown reduced HIF2α expression and increased phosphorylated epidermal growth factor (EGFR) expression in untreated tumor models." (PMID 33799686, 2021). "Similar tumor growth inhibition was found in imipramine with standard therapy erlotinib (EGFR inhibitor)." (PMID 34765548, 2021). "For example, patients with solid stage IV cancer types harboring amplification in the MDM2 family or EGFR aberrations who received anti-PD1/PDL1 immunotherapy showed increased tumor growth." (PMID 34771420, 2021). "Here, we addressed the pro-tumoral role of CD151 in NSCLC by targeting EGFR/ErbB2 which favors tumor proliferation, migration and invasion." (PMID 34108040, 2021). "Cetuximab is a human/mouse chimeric IgG1 monoclonal antibody that mainly binds to EGFR on the surface of tumor cells and competitively blocks EGFR signaling to inhibit tumor cell proliferation." (PMID 34925375, 2021). "For the untreated group (left), there was more EGFR expression in the tumour tissues; after treatment (mid and right), the expression of EGFR in the tumour decreased, and the proportion of positive cells was less than that in the control group." (PMID 34414172, 2021). "On the other hand, small leucine-rich proteoglycans like lumican and decorin serve as tumor suppressors by physically antagonizing RTK such as EGFR and c-Met (receptor for HGF), evoking antisurvival and proapoptotic pathways." (PMID 34976811, 2021). "Inhibition of EGFR suppressed the IL-9 induction in all Th cells and our data indicates that EGFR pathway is crucial for the anti-tumor functions of Th9 cells." (PMID 34075041, 2021). "While both tumor cell lines express high levels of the BiTE target antigen EGFR, expression of the CAR target antigen FR-α differed with intermediate levels in HCT116 and low expression in Panc-1." (PMID 33863363, 2021). "This study identified EGFRvIII in 39.5% of the tumour samples and 44.7% of the serum EV samples, whereas only 28.1% of the tumor biopsies co-expressed EGFR and EGFRvIII." (PMID 34205183, 2021). "Based on the ex vivo drug screening results, the patient’s tumor cells were selectively most sensitive to EGFR/HER2 inhibitors as a class of drugs." (PMID 34604070, 2021). "Further, Tregs express EGFR in inflamed tumor microenvironments, and the mast cell‐derived epidermal growth factor‐like amphiregulin enhances Treg immunosuppressive effects, a phenomenon inhibited by EGFR–TKIs." (PMID 34096184, 2021). "The composite nanoplatform (Fe3O4/Ag/C225) was used to be an EGFR-targeted tumor tracer for radiation therapy." (PMID 34322025, 2021). "Immunohistopathology stainings of tissue biopsies confirmed presence of proliferative tumor cells, and strong positivity for EGFR (membranous and cytoplasmic) in the resected residual tumor tissue." (PMID 34158840, 2021). "The work was the first to compare the anti-EGFR antibody, cetuximab and the anti-EGFR nanobody 7D12 side by side for the purpose of optical imaging and tumor-specific FGS." (PMID 33670740, 2021). "Other studies indicated that miR-338-5p interacted with the 3’ untranslated region of the EGFR oncogene and PIK3C3, a candidate tumor suppressor, however, other studies questioned this EGFR interaction." (PMID 33808624, 2021). "RT is also an important treatment modality for tumor lesions that progress upon EGFR or ALK Tyrosine kinase inhibitors (TKIs) or immune checkpoint inhibitors (ICI)." (PMID 33671073, 2021). "Initial investigations of sEVs from EGFR-mutant NSCLC tumor cells or pleural effusion (PE) fluid from patients with NSCLC or benign diseases showed different protein profiles for individual sEV samples." (PMID 33671772, 2021). "EGFR-targeted, doxorubicin-containing bacterial minicells were demonstrated to rapidly locate in spontaneous gliomas in dogs, a tumor usually difficult to reach because of the blood-brain barrier." (PMID 33761944, 2021).
tumor (continued). "FGFR-I monotherapy achieved partial response which was surprisingly good and this was not improved by adding CET, suggesting a switch in GF dependencies for tumor growth from EGFR to FGFR signaling in this tumor." (PMID 34271981, 2021). "Motolimod combined with cetuximab (anti-EGFR antibody), or conventional chemotherapy, can decrease the number of Tregs in the tumor microenvironment and increase in the number of circulating EGFR-specific CD8+ T cells." (PMID 34422051, 2021). "Mice implanted with high-EGFR-expressing MDA-MB-468 cells showed significant inhibition of tumor growth when treated with Rb-PEA15-AA protein compared with Rb-control." (PMID 34241740, 2021). "We also elucidated novel mechanisms for ILT4-mediated tumor immune escape in EGFR-activated NSCLC, involving recruitment of pro-tumor TAMs and inhibition of T cell immunity." (PMID 33537094, 2021). "In both in vitro and in vivo studies, a combination of the ER antagonist and the EGFR tyrosine kinase inhibitor has been shown to decrease cell proliferation and tumor growth more than monotherapy either with ER antagonists or EGFR TKI." (PMID 35008242, 2021). "Some immunotherapy targets are specific oncogenic mutations such as EGFR variant III (EGFRvIII), which seems to be exclusively expressed in tumour tissue." (PMID 34769211, 2021). "LAT011 and LAT015 both had a high calculated tumor burden but very low mutant EGFR AFs detected by either ddPCR or NGS." (PMID 34283064, 2021). "First, dual inhibition of both EGFR and cMet signaling by blocking ligand‐induced activation and inducing receptor degradation slows down tumor cell proliferation." (PMID 34431224, 2021). "Intracellular metabolic alterations have been observed upon treatment with EGFR TKIs and provides a rationale for investigating if targeting tumor metabolism adjuvant or concurrently with EGFR TKIs would improve therapeutic efficacy." (PMID 33668151, 2021). "More precisely, a dual EGFR/HER2 inhibitor with CTX plus Afatinib shows significantly improved tumor volume reduction in CTX-resistant xenografts compared with either agent alone in monotherapy." (PMID 33718169, 2021). "Combined, this literature supports the idea that EGFR/ERBB inhibition promotes the participation of the tumor immune microenvironment via induction of an interferon response program." (PMID 33485341, 2021). "The application of antibody-based imaging strategy on pediatric and rare HGG disease subgroups that express EGFR still need to be validated in animal tumor models and clinical studies." (PMID 33707521, 2021). "Increased or extended EGFR-dependent progenitor cells were found in tumor tissues of NF1-deficient mice and upregulation of EGFR stimulates the activation of the downstream signaling, the MAPK cascade." (PMID 34948100, 2021). "In line with a potential role promoting EGFR signaling by opposing receptor degradation, Cezanne-1 overexpression is predictive for aggressive tumor progression in human breast cancer." (PMID 35083168, 2021). "Several studies also showed that EGFR expression correlated with the advanced tumor node metastatic stage, clinical stage, and distant metastatic state of NPC patients by analyzing a cohort of clinical samples." (PMID 34578147, 2021). "The authors showed an increased delivery of siRNAs and fluorescent quantum dot nanocrystals both in vitro and in EGFR-positive tumor xenografts in mice." (PMID 33981364, 2021). "At an E:T ratio of 5:1, all seven distinct cattle-derived ultralong CDR-H3 bispecifics behaved quite similar with only subtle differences in eliciting lysis of EGFR-overexpressing tumor cells by PBMC-isolated NK cells from individual healthy donors." (PMID 35087526, 2021). "This is because EGFR mutations are the strongest predictive biomarker for PFS and tumor response to EGFR‐TKI treatment." (PMID 34477313, 2021).
tumor (continued). "Mice bearing orthotopic HGG xenografts with modest EGFR expression were imaged in vivo after systemic panitumumab-IRDye800 injection to assess its tumor-specific uptake macroscopically over 14 days, and microscopically ex vivo." (PMID 33707521, 2021). "Clinical studies of miRNAs in anti-EGFR therapy-treated CRC patients assessed only the miRNA expression in tumor tissue." (PMID 34208056, 2021). "EPA and DHA have been shown to reduce VEGF levels and inhibit the expression of epidermal growth factor receptor (EGFR) in tumor lipid raft microdomains and membrane phospholipids, as well as promote tumor apoptosis and block migration and metastasis." (PMID 33805447, 2021). "For instance, basis 1 contains classic housekeeping genes, such as GAPDH and ribosomal protein genes (RP-); basis 3 contains well-known tumor-related genes, including EGFR and CDK4." (PMID 34252925, 2021). "The response rate in EGFR-mutant NSCLC tumours was found to be only 16% in this study, i.e., a 16% precision." (PMID 34680436, 2021). "In this report, we observed that SHP-1, a tumor suppressor, directly interacts with EGFR and suppresses its induction of Ras/Erk/GSK3β signaling and its downstream cell cycle and EMT signals." (PMID 34591414, 2021). "Ordinarily, the EGFR pathway stimulates tumour cell proliferation, migration, adhesion, and angiogenesis and inhibits apoptosis." (PMID 34221011, 2021). "For curative treatment, one strategy for drastically reducing the number of remaining tumor cells and preventing the development of drug resistance is to combine EGFR-TKI with other therapeutic agents." (PMID 34831415, 2021). "According to the pathology report, the original EGFR‐sensitizing mutation was detected in all FFPE samples, while the T790M mutation was present in 15 tumor samples (43%)." (PMID 33107189, 2021). "The usefulness of primary tumour location for the basis of anti-EGFR treatment decisions warrants further exploration." (PMID 34188197, 2021). "Findings have also revealed good correlation between mutations found in GBM, e.g., PDGFRA, IDH1, EGFR, and NF1—and the tumor’s metabolic fingerprint." (PMID 34068300, 2021). "The peculiar low affinity enables the antibody to bind only transiently to its target on normal tissue wherein the EGFR density is low compared to EGFR-overexpressing tumor cells, minimizing adverse effects." (PMID 34206707, 2021). "Corresponding immunohistochemistry sections had positive EGFR staining in both tumor cells and endothelial cells." (PMID 34680445, 2021). "Mice implanted with EGFR-low cells had larger tumor volumes throughout the experiment than the mice with EGFR-high cells." (PMID 32989241, 2021). "The administration of emetine decreased tumor growth by 77% with reduced amounts of EGFR and MCL1 proteins." (PMID 34203709, 2021). "For example, EVs secreted by cancer cells were reported to transfer mutant EGFR to tumor endothelial cells, promoting mitogenic MAPK and AKT signaling." (PMID 34283059, 2021). "Several studies have reported evidence of EMT in tumor specimens obtained from patients who developed AR to first-generation EGFR-TKIs." (PMID 33572269, 2021). "Although the trial was terminated early due to poor recruitment, these findings suggest improved anti-tumour activity for tepotinib plus gefitinib compared to standard chemotherapy in patients with EGFR-mutant NSCLC and MET amplification." (PMID 34898564, 2021). "The epidermal growth factor receptor (EGFR)/focal adhesion kinase (FAK)/nuclear factor (NF) -kB pathways are mechanisms by which tumor cells promote proliferation, inhibit apoptosis, and induce drug efflux protein expression." (PMID 34360968, 2021). "Prospective next-generation sequencing (NGS) of 70 cancer-related genes, including EGFR, via plasma circulating tumor DNA (ctDNA) was performed." (PMID 34140248, 2021). "In NPC cells, the abnormal expression of EGFR regulates the cell cycle and tumor growth by related genes." (PMID 34578147, 2021).
tumor (continued). "Recently studies have also shown that EGFRvIII can be eliminated from extrachromosomal DNA of tumor cells as a resistance mechanism when tumor cells are treated with EGFR TKIs." (PMID 34926242, 2021). "This notion is also supported by our observation of response towards anti-EGFR therapy in earlier tumor stage CRC PDX models." (PMID 34271981, 2021). "For instance, EGFR and c-MET (receptor for hepatocyte growth factor) are implicated in various cellular processes and regulated by many miRNAs, leading to tumor progression." (PMID 34830377, 2021). "We compared the expression of SPP1 in LUAD tumor and normal tissues, and in samples with wild-type and mutant EGFR." (PMID 34178613, 2021). "Beyond anti-EGFR treatments, patients with BRAFV600E tumours were treated with immunotherapy for anti-PD-L1 in the CheckMate 142 clinical trial, as it was shown that PD-L1 is upregulated by EGFR activation." (PMID 34945008, 2021). "The overactivation of the EGFR-signaling pathway is frequently involved in tumor initiation, growth, and metastasis." (PMID 34572013, 2021). "Several studies have reported that CD44, and especially the CD44 splice isoform CD44s, positively correlates with EGFR tumor signatures and predicts poor survival in different types of cancers." (PMID 33981532, 2021). "In xenograft mouse models of malignant pleural mesothelioma and NSCLC, the tumor-targeted delivery of miR-16 by using a EGFR-targeted EnGeneIC Delivery Vehicle (EDV) and nanocell delivery system (TargomiRs) significantly reduced tumor growth." (PMID 33672261, 2021). "Wt EGFR overexpressing tumours, with gene amplification of the wt EGFR gene, were too low in number to be included in this study." (PMID 35052732, 2021). "The application of EGF, the natural ligand of EGFR, is a potential strategy to target every subset of tumor cell expressing wild-type EGFR as well as its mutant forms." (PMID 33916177, 2021). "In this study, we explored the anti-tumor effect of SH-1028 in vitro and in vivo, the inhibition of cell signal, such as EGFR and ERK phosphorylation, and verified the relationship between the pharmacokinetics and pharmacodynamic responses." (PMID 33986687, 2021). "EGFR, which plays an important role in tumor metastasis is found to be highly expressed in a variety of tumors, such as breast, colon, gastric, pancreatic, ovarian, and prostate cancers, gliomas, and melanomas." (PMID 33922139, 2021). "Meanwhile, activated MAPK/ERK pathway would upregulate the expression of EGFR, thus forming an autocrine loop that promotes the growth of tumor cells and plays a positive feedback role." (PMID 34858869, 2021). "To identify mechanisms by which Gi/o-GPCRs regulate HER2 tumor development and progression, we assessed the activation status of EGFR and HER2 and their downstream effectors." (PMID 34343132, 2021). "Our work suggests that GSK3α- and ARIH1-activating agents, as well as EGFR inhibitors, are likely to stimulate anti-tumor immunity and therefore enhance existing cancer therapies by triggering the PD-L1 degradation pathway this work delineates." (PMID 33879767, 2021). "EGFR activation has been associated with a down regulation of MHC-I and the antigen processing machinery, making tumor cells less sensitive to the immune system attack." (PMID 34211836, 2021). "As shown, for half of the patients from the ID-MUT study, the EGFR genotyping result was determined to be 6–7 cd (4–5 wd) after the tumor sampling with the IdyllaTM method, against 19–20 cd (13–14 wd) for the NGS method." (PMID 34898548, 2021). "Overexpression of EGFR is related to survival, invasion, metastasis, drug resistance, and poor prognosis of tumor, for example, EGFR is considered as an indicator of inferior prognosis in node-negative breast cancer." (PMID 34335109, 2021).
tumor (continued). "In summary, GFHPD consumption efficiently reduced PD-1 and PDL-1 immune-checkpoint protein expression to a comparable extent as anti-EGFR Ab therapy, suggesting both therapeutic regimens to boost anti-tumor T-cell responses." (PMID 34830971, 2021). "Epithelial–mesenchymal transition (EMT) induces tumor progression and drug resistance to various cytotoxic and targeted drugs, including EGFR‐TKIs." (PMID 33939301, 2021). "One of the best-established mechanisms is the development of mutations in the EGFR extracellular domain (ECD), occurring in approximately 20% of CRCs following EGFR blockade, which interfere with antibody binding, leading to tumor relapse." (PMID 34943612, 2021). "Acquired EGFR amplifications have also been detected in tumor samples from patients whose tumors developed resistance to MET TKIs." (PMID 34425853, 2021). "This study examined the functional importance of EGFR and the molecular mechanisms regulating EGFR in tumor cluster formation, and then evaluated the therapeutic potential of the new anti-EGFR antibody LA1 in blocking metastasis of TNBC in vivo." (PMID 33995681, 2021). "Another example of potential tumour heterogeneity can be seen in P03, who also had an amplification of EGFR detected in both plasma and tissue." (PMID 33539436, 2021). "Materials and Methods: We detected EGFR and KRAS mutations in paired plasma and tumor tissue samples from 147 NSCLC patients." (PMID 33442424, 2021). "From a clinical point of view, we expect that cytotoxicity will be mostly confined to EGFR-overexpressing tumor cells, similarly to what happens for most therapeutic agents against targets preferentially but not exclusively expressed in tumors." (PMID 34294133, 2021). "The tumor evolution analysis showed that CSF carried significantly fewer clusters, but subclonal proportion of EGFR was remarkably increased with tumor progression." (PMID 34642306, 2021). "HER3-DXd demonstrated to inhibit tumor growth in HER3+, EGFR-mutated, EGFR-TKI resistant patient-derived xenograft (PDX) models, while it was ineffective in HER3-negative models." (PMID 33509252, 2021). "We observed a significant depletion of B cells in EGFR-MT compared to EGFR-WT (r = −6.23), suggesting that EGFR-MT tumor has a lower proportion of tumor-infiltrating B cells than EGFR-WT." (PMID 34663810, 2021). "All Exon20ins patients who were treated with first-line EGFR TKIs (n = 6) showed progressive disease as the best tumor response." (PMID 34680280, 2021). "Collectively, these results reveal that knockdown of KTN1 reduces EGFR protein expression post-transcriptionally and serves as a tumor suppressor strategy by increasing apoptosis and repressing the survival fraction in cSCC cells." (PMID 34689164, 2021). "The majority of non-small cell lung cancer (NSCLC) tumours express epidermal growth factor receptor (EGFR), which allows for precise and targeted therapy in these patients." (PMID 34069119, 2021). "Since ASPN regulates GC metastasis through activation of EGFR and the ERK-CD44/MMP-2 pathway, it perhaps favourably associates with TGFB1 and activates the signaling pathway to promote tumor growth and progression." (PMID 34379688, 2021). "When the tumor volume reached 50–100 mm3, mice were intraperitoneally injected with 10 mg/kg cetuximab, ramucirumab, anti-EGFR/VEGFR2 BsAb or saline twice a week." (PMID 33804477, 2021). "The CD44+EGFR+ double-positive tumor cells (Q2) showed highest cluster formation ability compared to the CD44+EGFR- single-positive cells (Q4) or CD44-EGFR- double-negative cells (Q3)." (PMID 33995681, 2021). "For example, EGFR inhibitors attenuate the transcriptional inactivation of PDGFR operated by EGFRvIII in tumor cells, thus enabling cells to switch to PDGFR-mediated pro-tumoral signaling." (PMID 34063168, 2021). "Activation of the EGFR signalling cascade appears to play a pivotal role in tumour proliferation, infiltration and metastasis." (PMID 34868634, 2021).